GATA4 (GATA binding protein 4)
Diseases named in the same sentence as GATA4 in open-access papers (continued):
Sharing a sentence is not in itself a finding about the gene and the disease.
congenital heart disease (68 papers, 2007 to 2026). A heart disease that is present at birth. "The GATA4 gene is essential for fetal heart development, and pathogenic GATA4 variants are a known cause of structural congenital heart diseases." (PMID 41099604, 2026). "This study describes the identification of a novel heterozygous missense variant in the GATA4 gene (c.907G>T; p.Gly303Trp) in a family affected by congenital heart defects, specifically septal anomalies and pulmonary stenosis." (PMID 40430071, 2025). "Subsequently, genetic testing including Array-CGH, was conducted and revealed a deletion of chromosome 8 involving the GATA4 gene, which is associated with a condition characterised by neonatal diabetes, congenital heart disease, and pancreatic hypoplasia." (PMID 39457190, 2024). "In recent years, GATA4 variants have been identified in patients with congenital heart disease(CHD) with various complications." (PMID 39285472, 2024). "Mutations in the GATA4 gene have been linked to a range of congenital heart diseases in humans, such as cardiac septal defects, tetralogy of Fallot, and patent ductus arteriosus." (PMID 39240962, 2024). "The synergistic activation between HAND2 and GATA4 TFs is causally linked to congenital heart diseases (CHD)." (PMID 37359008, 2023). "Mutations in the GATA4 gene have been linked to a range of congenital heart diseases in humans, such as cardiac septal defects, tetralogy of Fallot, amd patent ductus arteriosus." (PMID 37961530, 2023). "In embryonic heart tissue, we found GATA4, 5, and 6 —known regulators of cardiac development and growth that, when perturbed, have been implicated in human congenital heart disease." (PMID 36040971, 2022). "Gata4 is an essential cardiac transcription factor whose deletion can cause congenital heart disease." (PMID 35736907, 2022). "In previous studies, we have found several GATA4 gene regulatory variants in patients with congenital heart disease." (PMID 33865372, 2021). "GATA4 gene mutations have been associated with several human diseases, including congenital heart disease, coronary artery disease, hypertension, type 1 diabetes and various cancers." (PMID 33865372, 2021). "In humans, variants in GATA4 (MIM# 600576) were first identified in patients with congenital heart disease (CHD) including Atrial ventricular septal defects (AVSD) and Tetralogy of Fallot (TOF)." (PMID 31962012, 2020). "NKX2‐5 and GATA4 were the first congenital heart disease–causing genes identified by linkage analysis." (PMID 30834692, 2019). "The findings, together with the previous data, imply that GATA4 variants primarily cause congenital heart disease and rarely result in 46,XY disorder of sex development." (PMID 30455927, 2018). "The co-appearance of congenital heart disease and testicular anomalies was found in a family with a GATA4 p.Gly221Arg mutation, thought to disrupt interaction with FOG2 and/or NR5A1, important factors for gonadal development." (PMID 28541271, 2017). "Over 90 point mutations in GATA4 have been associated with human congenital heart disease with the majority found in the two zinc fingers and C-terminal domains." (PMID 26642209, 2015). "In spite of higher number of CHD in India, there are very few studies to find a link between GATA4 mutation and congenital heart disease." (PMID 25928801, 2015). "Over 20 point mutations in the C-terminal zinc finger of GATA4 have been reported in patients with congenital heart disease." (PMID 26642209, 2015). "The importance of the interaction of GATA4 and Tbx5 for heart development has been suggested by human genetics studies which have reported patients with congenital heart disease carrying the G296S mutation in the GATA4 protein." (PMID 25241353, 2014).
congenital heart disease (continued). "In particular, mutation G296S in the human GATA4 has been associated with congenital heart defects, highlighting the importance of intact GATA4 for heart development." (PMID 25241353, 2014). "Accordingly, these observations seem to point to delineable differences between CAD and congenital heart disease in their interactions with the GATA4 variants." (PMID 24330461, 2013). "In summary, our study identified the GATA4 transcription factor as an independent risk factor for congenital heart disease and CAD/MI and a metabolic risk trait for cardiovascular diseases." (PMID 24330461, 2013). "One of these suggests an impediment of the GATA4 transcription activity in congenital heart disease as involving at least two of the variants, p.A348A and p.S377G, which were also included in the present study." (PMID 24330461, 2013). "While this manuscript was under revision there was a report describing a family where a GATA4 missense mutation segregated with congenital heart disease and 46,XY DSD." (PMID 21408189, 2011). "Mutations in the GATA4 gene have been found in patients with congenital heart defects, but no mutations have been related to upper-limb malformations so far." (PMID 21637475, 2010). "Mutations in the development regulatory gene GATA-4, located on human chromosome 8p23.1-p22, have been found to be responsible for some cases of congenital heart defects including PFO." (PMID 19018306, 2008). "Functional studies have shown a role for the GATA-4 gene in cardiac embryogenesis and mutations in this gene have been found to be associated with congenital heart defects such as atrial septal defect (ASD) and patent foramen ovale (PFO)." (PMID 19018306, 2008). "Numerous studies have shown that mutations in the GATA-4 gene have a significative role in cardiogenesis and are associated with congenital heart defects, like PFO." (PMID 19018306, 2008). "In humans, four GATA4 gene mutations have been identified in families with congenital heart defects (CHD) notably, atrial septal defects." (PMID 17592645, 2007). "Meanwhile, normal Gata4 and Nkx2-5 activities might drive normal cardiac development and the mutation events on Gata4 and Nkx2-5 were considered as the causes of the occurrence and development of congenital heart disease." (PMID 36318264, 2023). "Mutations in GATA4 gene may cause congenital heart diseases such as the tetralogy of Fallot, atrial septal defect, ventricular septal defect, atrioventricular septal defect, and dilated cardiomyopathy." (PMID 31192139, 2019). "In human, GATA4 mutations can lead to many kinds of congenital heart diseases." (PMID 27391137, 2016). "In accordance with previous findings on GATA4 mutation screening and in vitro experiments, this study confirms that GATA4 M310V mutation may lead to the development of the congenital heart defect, ASD." (PMID 25873328, 2015). "Another example of a physiologically important partnering of GATA4 was provided by the finding that the G296S mutation affects the interaction between GATA4 and Tbx5 and it leads to congenital heart disease in patients, while in homozygous mutant mice it causes mid-gestation lethality." (PMID 25241353, 2014). "TNKS1 is implicated in behavioral anomalies, SOX7 in developmental delay, and GATA4 in concert with SOX7 might cause congenital heart disease." (PMID 25520754, 2014). "It has been well-documented that mutations in GATA4 are associated with a number of congenital heart defects including ventricular septal defect, atrial septal defect, Tetralogy of Fallot, endocardial cushion defect, right ventricular hypoplasia, and double-inlet left ventricle." (PMID 23554720, 2011). "Notably, by far, the majority of GATA4 mutations studied to date seem to point to their influencing its transcriptional activity, and have been associated primarily with cardiac malformations, such as congenital heart disease." (PMID 24330461, 2013).
congenital heart disease (continued). "In summary, the Gata4 G295S mutation functions as a hypomorph in vivo and leads to defects in cardiomyocyte proliferation during embryogenesis, which may contribute to the development of congenital heart defects in humans." (PMID 22589735, 2012). "The association with the genes NKX2-5, NOTCH1, GATA4, GATA6 and HAND1 links trabeculation to congenital heart disease (CHD)." (PMID 39567769, 2024). "GATA-binding protein 4 (GATA4) is a transcription factor which is known to be involved in the development of some forms of congenital heart disease." (PMID 35909548, 2022). "Gata4 is an essential transcription factor during heart development, and it is presumed that alterations of Gata4 expression can affect the epigenetic regulation of embryonic development and contribute to congenital heart disease in children." (PMID 34356111, 2021). "Our previous researches have found that five mutation sites in GATA4 gene promoter, two mutation sites in GATA5 gene promoter, and two mutation sites in GATA6 gene promoter were associated with congenital heart disease." (PMID 33684162, 2021). "Other genes encoding GATA family cardiac factors, such as GATA4 (GATA-binding protein, 4; 8p23.1; OMIM*6005769) and GATA6 (GATA-binding protein, 6; 18q11.2; OMIM*601656) were observed in human congenital heart defects." (PMID 28883797, 2017). "Our previous study indicated that 8 patients from a family with a history of congenital heart disease had simple atrial septal defect (ASD) and carried the same mutation at codon 310 in the GATA4 gene." (PMID 25873328, 2015). "Transcription factor GATA4 is a dosage sensitive regulator of heart development and alterations in its level or activity lead to congenital heart disease (CHD)." (PMID 26642209, 2015). "The functionally impaired GATA4 mutants identified in this study should contribute to the progress being made in the early diagnosis and prevention of congenital heart defects." (PMID 23626780, 2013). "The generation of the Gata4 G295Ski mice provides a mouse model to study human congenital heart defects." (PMID 22589735, 2012). "We screened the TBX5, GATA4, and NKX2.5 genes for mutations, by direct sequencing, in 32 unrelated patients presenting classical or atypical HOS, isolated congenital heart defects or isolated upper-limb malformations." (PMID 21637475, 2010). "To gain insights into congenital heart disease (CHD), we have been analyzing cardiac-specific transcription factor genes, including GATA4, which encodes a zinc finger transcription factor." (PMID 17592645, 2007). "Pathogenic GATA4 sequence variants with isolated diaphragmatic hernia in the absence of congenital heart defects are extremely rare." (PMID 41099604, 2026). "Congenital heart disease (CHD) represents a prevalent group of structural cardiac anomalies often associated with alterations in key transcription factors including NKX2-5, TBX5, and, particularly, GATA4." (PMID 40430071, 2025). "As an important cardiac transcription factor regulating cardiac development, overexpression of GATA4 may have a substantial impact on cardiac development resulting in congenital heart disease." (PMID 41347213, 2025). "In a family of individuals with mutations in GATA4, 46,XY DSD and congenital heart disease, AMH levels were consistently low and functional analysis demonstrated that mutations in GATA4 may reduce the action of the AMH promoter." (PMID 35909548, 2022). "GATA4 also has been found to be a human candidate gene relevant to congenital heart disease." (PMID 33308225, 2020).
congenital heart disease (continued). "In addition to two polymorphisms of NKX2‐5 (rs2277923, rs28936670) variant in the cardiac septal defect, two variants in GATA4 (rs368418329, rs56166237) and one variant in TBX5 (rs6489957) seem to have a role in the pathogenesis of congenital heart disease." (PMID 30834692, 2019). "Results showed that NKX2.5, GATA4, and FOG2 were susceptibility genes of congenital heart disease." (PMID 27118988, 2016). "GATA4 is a dosage-sensitive regulator of heart development and changes in GATA4 protein levels or activity may lead to congenital heart disease." (PMID 26642209, 2015). "Since GATA4 constitutes an established risk gene for congenital heart disease, it was necessary to rule out the likelihood of such potential relationships masking those pertaining to disease trait-gene interactions under investigation." (PMID 24330461, 2013). "The GATA4 gene at 8p23.1-pter has been implicated in all such cases with a heart defect but not in patients without heart defects." (PMID 21406098, 2011). "On the other hand, it seems that the role of genes, such as GATA4, TBX5, NKX2-5, HOMEZ, PLAGL1, and CITED2, in heart development is significant, as numerous studies on knockout mice report that mutations in these genes are frequently associated with VSD or other congenital heart anomalies." (PMID 39466144, 2025). "A large proportion of these variants were previously reported in association with congenital heart defects (CHD) but a lack of supporting evidence led us to classify many of these GATA4 and ZFPM2 variants as variants of unknown significance (VUS)." (PMID 31962012, 2020). "Even though no gross malformation was observed in adult Pdgfd-/- heart tissue, we found reduced mRNA expression of Gata4 and Notch1, two genes involved in cardiac development, maintenance of adult cardiac function and control of cell fate and differentiation, as well as in congenital heart disease." (PMID 27032083, 2016). "Therefore, our study does not only furnish strong support for an important role for these SNPs in congenital heart disease, but also points to a possible sharing of common disease pathways involved in the etiologies of CAD and congenital heart disease at the GATA4 signaling level." (PMID 24330461, 2013). "Previous reports have shown that GATA4 and TBX5 have a significant impact on congenital heart disease." (PMID 39375485, 2024). "Therefore, the expression and the role of GATA5 partially overlap that of GATA4 and GATA6 during development, making it an important molecular factor for different congenital heart diseases." (PMID 40076735, 2025). "Consistent with normal expression of GATA4 that functions in cardiac development the patient does not have congenital heart disease." (PMID 25520754, 2014). "Thus, the difference in the nature of the congenital heart disease and CAD etiologies renders it very intriguing why these two disorders would share the GATA4, or any other signalling pathway for that matter, as a common disease pathway." (PMID 24330461, 2013). "There were no signs of GATA4-related congenital heart defects." (PMID 41099604, 2026). "Although NEXN variants have not previously been described in cases of complex congenital heart disease, such as TGA, gain-of-function NEXN variants resulting in GATA4 suppression have been described as the cause of secundum atrial septal defects in both mouse models and humans." (PMID 41347213, 2025). "Notably, GATA4 duplications are often inherited from parents without congenital heart disease and are present in unselected control genotypes." (PMID 39925442, 2025). "In other cases, when congenital heart disease was also not observed (Cases 1 to 7), the copy number of genes SOX7 and GATA4 was not changed." (PMID 35327368, 2022).
heart failure (45 papers, 2009 to 2026). Inability of the heart to pump blood at an adequate rate to meet tissue metabolic requirements. "Consistently, there is also evidence that the GATA4 signaling pathway is associated with aging-related diseases, including atherosclerosis and heart failure." (PMID 36177479, 2022). "Loss of Gata4 from the heart also negatively impacted neoangiogenesis following stress stimulation, further defining its role in homeostasis and prevention of heart failure." (PMID 24391969, 2013). "Gata4 is not only indispensable for maintaining the survival of ventricular myocytes but also forms a positive feedback loop with Nkx2.5 to jointly regulate heart development; its functional deficiency is closely related to heart failure." (PMID 41154801, 2025). "As in the neonatal Gata4/6 loss-of-function experiment, Myh7 and Nppa were highly upregulated in GATA4/6 knockout hearts, while Myh6 was highly downregulated, consistent with changes observed in heart failure." (PMID 26023924, 2015). "Recruitment of SUV39H1 to the GATA4 promoter suppressed the GATA4 transcription by triggering H3K9me3 modification, which attenuated hypertrophy and heart failure in mice." (PMID 36193085, 2022). "Superoxide dismutase enzymes, catalase, glutathione peroxidase, gap junction protein alpha, myosin heavy chains, and zinc finger transcription factor GATA4 were located upstream of several genes in heart failure network." (PMID 35311161, 2022). "We have previously demonstrated that the transcriptional co-activator, p300, localized in the nucleus of cardiomyocytes, induces the acetylation of GATA4 during the development of heart failure." (PMID 35173540, 2022). "The results of this study suggested that the inhibition of GATA4 homomultimerization can serve as a possible therapeutic strategy and preventive measure for heart failure." (PMID 35173540, 2022). "The development of drugs that specifically inhibit GATA4 multimerization is a promising novel approach to the treatment of heart failure." (PMID 35173540, 2022). "Lastly, we found that a known human cardiomyopathy-causing GATA4 mutant reduces PGC-1/ERRγ/GATA4 cooperativity and that many GATA-dependent and GATA4-independent ERR target genes are downregulated in ventricular samples from humans with heart failure." (PMID 35418170, 2022). "Cardiomyocyte specific deletion of GATA-4 or GATA-6 in adult mice leads to heart failure during pathological pressure overload." (PMID 33876316, 2021). "The cooperation of p300/GATA4 and acetylation of GATA4 are critical events in cardiomyocyte hypertrophy and the development of heart failure." (PMID 34444769, 2021). "Our results are also in agreement with earlier findings suggesting that GATA4-based gene transfer represents a novel and efficient therapeutic approach for the treatment of heart failure." (PMID 32586406, 2020). "In the present study, our results showed that the binding of total AcH3, as well as the subtype AcH3K9, was reduced, and that the binding of active transcription factors GATA4 and Mef2c was decreased near the Atp2a2 promoter region after heart failure." (PMID 30286210, 2018). "Ankyrin repeat domain 1 (Ankrd1), a transcriptional regulator of Gata4 signaling which is consistently increased in human heart failure, was found to be diminished by 2.5-fold (p < 0.001) in knockout heart tissue." (PMID 28673258, 2017). "To further characterize functional interactions between Bnip3-p300 and GATA4, we measured the transcript level of atrial natriuretic protein (ANP), a gene that is regulated by p300-GATA4 and a marker of heart failure." (PMID 26317696, 2015). "Curcumin was also found to be a novel heart failure therapy by the GATA4/p300 transcriptional signal pathway which is recognized as a critical role in the cardiomyocyte hypertrophy and heart failure therapy." (PMID 26007179, 2015).